MSTN (myostatin)
Diseases named in the same sentence as MSTN in open-access papers (continued):
Sharing a sentence is not in itself a finding about the gene and the disease.
metabolic disorders (26 papers, 2009 to 2026). "Genetic disruption of myostatin or its related signaling is known to cause strong protection against diet-induced metabolic disorders." (PMID 23936482, 2013). "Although correlations emerged between myostatin and cardiometabolic biomarkers, further studies are needed to elucidate the clinical relevance of these relationships for the preservation of age-related muscle loss and metabolic disease." (PMID 35287731, 2022). "Myostatin may be used as a biomarker for metabolic disorders, and higher serum myostatin is associated with favorable metabolic profiles." (PMID 25254550, 2014). "Furthermore, disturbances in irisin, MSTN, and adiponectin levels—factors involved in muscle-adipose tissue crosstalk—may indicate an increased risk for the development of metabolic disorders in patients with PWS later in life." (PMID 41303309, 2025). "Thus, higher serum myostatin was associated with better risk profile for metabolic disorders." (PMID 25254550, 2014). "MSTN’s relationship with muscle growth has led to the widespread study of its inhibition for the treatment of muscle, bone, and metabolic diseases, as well as enhancing agricultural meat production." (PMID 39340593, 2025). "MSTN inhibition for the treatment of metabolic disorders in humans has already shown moderate success in clinical trials with bimagrumab." (PMID 39340593, 2025). "Further research is required to fully elucidate the interactions between MSTN inhibition and metabolic disorders." (PMID 39340593, 2025). "Beyond skeletal muscle, myostatin has been shown to affect the CNS by reducing neurogenesis and synaptic plasticity, contributing to cognitive decline observed in metabolic disease." (PMID 41305665, 2025). "It is important to treat muscle atrophy and metabolic disorders by targeting the myostatin signaling pathway." (PMID 36611855, 2022). "Numerous studies have shown that myostatin signaling is another important target for the treatment of muscle wasting and metabolic disorders." (PMID 36611855, 2022). "Based on this postnatal function of MSTN, numerous pharmaceutical and biotechnology companies have developed MSTN inhibitors that have been tested in clinical trials in patients with muscle and metabolic diseases." (PMID 35287700, 2022). "This reduction in muscle mass, mediated by myostatin, facilitates the appearance of metabolic disorders, such as resistance to insulin and accumulation of fat in the liver, since skeletal muscle is the main source of glucose-dependent glucose uptake." (PMID 33807959, 2021). "This supports the pharmacological inhibition of MSTN as a potential therapy for age-related sarcopenia and metabolic diseases." (PMID 32398787, 2020). "This is in striking contrast to the global hypoadiposity found in mice with life-long genetic myostatin blockade, but in line with a recent study on diet-induced metabolic disorders in mice with adult age myostatin deletion." (PMID 23936482, 2013). "Understanding this context-dependent regulation may help identify optimal strategies for targeting myostatin to preserve muscle mass and cognitive function in metabolic disease." (PMID 41305665, 2025). "One example of this is the antagonism of myostatin, which was used to prevent/reverse muscle wasting, but could be extrapolated further to metabolic disease applications." (PMID 35563026, 2022). "However, the analyses here along with the growing number of studies observing myostatin as a biomarker in the context of chronic and metabolic diseases reveals the complex and somewhat unpredictable behavior of the myokine." (PMID 32652899, 2020). "We show here that myostatin, a muscle-secreted growth and differentiation factor, may be a potential therapeutic target for the prevention and treatment of these metabolic disorders." (PMID 23936482, 2013). "Our results indicate that both liver and endothelium are direct targets of myostatin which may be involved in diet-induced metabolic disorders." (PMID 23936482, 2013).
metabolic disorders (continued). "Further study of myostatin may provide a novel therapeutic pathway for the treatment of metabolic disorders; however, it is vital that the influence of nutrition and gender should be taken into consideration." (PMID 20482891, 2010). "Consequently, further study of myostatin may provide a novel therapeutic pathway for the treatment of metabolic disorders; however, it is vital that the influence of nutrition and gender should be taken into consideration." (PMID 20482891, 2010). "The investigated parameters related to metabolic disorders included sirtuin 1 (SIRT-1), sirtuin 3 (SIRT-3), sirtuin 6 (SIRT-6), irisin (IRS), myostatin (MSTN), peptide YY (PYY), glucagon-like peptide 1 (GLP-1), and dipeptidyl peptidase 4 (DPP-4)." (PMID 39124846, 2024). "Present at the origin of several metabolic disorders, myostatin has negative effects on metabolism, and its levels are increased with physical inactivity and high levels of fat mass." (PMID 33807959, 2021).
neuromuscular disease (20 papers, 2010 to 2025). "Third, a low expression level of myostatin in neuromuscular diseases was detected, which translates to the loss of the target for myostatin pathway inhibition." (PMID 36012334, 2022). "In this sense, the role of serum follistatin as a biomarker for neuromuscular diseases is less clear compared to myostatin, with some studies reporting normal levels, while others indicate increased levels compared to controls." (PMID 38487549, 2024). "Myostatin has been suggested as a potential biomarker for monitoring disease progression in several neuromuscular diseases, including SMA." (PMID 39201450, 2024). "Myostatin inhibitory drugs have been tried in many neuromuscular diseases, but increases in muscle mass and strength are less likely to be expected." (PMID 37830636, 2023). "Myostatin is a potent inhibitor gene of muscle hypertrophy, and its inhibitors have been tried in many neuromuscular diseases." (PMID 37830636, 2023). "The downregulation of the myostatin pathway in neuromuscular disease explains the ineffectiveness of previous clinical trials." (PMID 36012334, 2022). "The murine hypermuscular myostatin knockout (Mstn−/−, also denominated ‘the myostatin-null’) described in 1997, has subsequently been further examined and crossed with various mouse models of neuromuscular diseases." (PMID 33802348, 2021). "All these novel findings greatly expand the understanding of myostatin in neuromuscular diseases and prove its viability as a biomarker in these conditions." (PMID 32796600, 2020). "A decreased mRNA level of the myostatin pathway in muscle biopsies, as well as low levels of circulating myostatin in several neuromuscular diseases, were found." (PMID 32691346, 2020). "Several myostatin inhibitory drugs have been evaluated in neuromuscular diseases, but so far, the clinical results are limited." (PMID 32961888, 2020). "Recent data from patients with neuromuscular diseases have indicated that circulating concentrations of myostatin are decreased with disease." (PMID 30481286, 2019). "Several recent reports have indicated that serum myostatin concentrations are decreased in animals and patients with neuromuscular diseases, raising the possibility that myostatin inhibition is unlikely to be effective in these populations." (PMID 30481286, 2019). "Our data show that in several neuromuscular diseases the myostatin pathway is shut down at mRNA level in muscle biopsies, leading to low levels of circulating and endogenous muscle myostatin and high-levels of follistatin." (PMID 29192144, 2017). "Electrical impedance myography (EIM) is sensitive to neuromuscular disease progression as well as to therapeutic interventions including myostatin inhibition and antisense oligonucleotide-based treatments." (PMID 26986564, 2016). "These agents have unequivocally increased muscle mass in murine models of health and neuromuscular disease and validated myostatin as a key regulator of muscle maintenance in adulthood and even later life." (PMID 20593012, 2010). "First, it is not fully understood how serum levels of myostatin relate to muscle levels in neuromuscular diseases such as SMA, and longitudinal data in untreated patients that could be used as comparators are scanty." (PMID 40368588, 2025). "In the future, it may be beneficial for researchers to study myostatin inhibitors such as taldefgrobep in other neuromuscular diseases." (PMID 39408601, 2024). "However, in several neuromuscular diseases, downregulation of the MSTN pathway has only partially been successful." (PMID 33546660, 2021). "It was proposed that myostatin levels could be a clinically meaningful, reflecting the global muscle health biomarker in other neuromuscular diseases." (PMID 32906621, 2020). "Downregulation of the myostatin pathway in neuromuscular diseases may be part of the explanation for this low clinical efficacy." (PMID 32906621, 2020).
neuromuscular disease (continued). "Finally, one of the most important questions raised by our work concerns the usefulness of blocking the myostatin pathway in diseases in general and in neuromuscular diseases in particular." (PMID 29192144, 2017). "In addition, myostatin is naturally downregulated in many neuromuscular diseases." (PMID 34790118, 2021). "Indeed, we have observed that whole myostatin pathway is strongly altered in the most atrophying neuromuscular diseases, at both mRNA and protein levels, and that the lower expression of serum myostatin is associated with a reduced muscle expression of GDF8 mRNA." (PMID 29192144, 2017). "Serum concentrations of myostatin (MSTN or GDF8), follistatin (FSTN), GDF11 and ACTIVIN A were determined in patients affected by several neuromuscular diseases with various levels of muscle atrophy and in controls." (PMID 29192144, 2017). "However, in the most wasting neuromuscular diseases such as DMD, the whole myostatin pathway is down-regulated." (PMID 29192144, 2017). "Concerning the neuromuscular diseases, in slowly progressive pathologies such as BMD or FSHD, an important variability of both myostatin and follistatin circulating proteins is observed across samples, suggesting that at least some patients may be eligible for an anti-myostatin approach." (PMID 29192144, 2017). "Myostatin is produced in the muscle, and as muscles from patients and animals with neuromuscular diseases are often smaller than healthy muscles, one possibility is that reduced circulating myostatin is simply due to reduced muscle size and not reduced production of myostatin per unit muscle mass." (PMID 30481286, 2019).
myopathies (15 papers, 2007 to 2025). "Therefore, it will be important for investigating the myopathies that are susceptible to myostatin antagonism, and, conversely, for identifying the stages of the disease at which the myostatin blockade is operative." (PMID 19412331, 2007). "Owing to its role as major regulator of muscle growth and its utility as biomarker in diverse myopathies, we selected myostatin (Mstn)." (PMID 38516893, 2024). "The findings in this study add to the application of growth factors in future studies of myopathies, as additional acceleration of regeneration by a combination of myostatin inhibitors and growth factors should be examined further." (PMID 35203514, 2022). "Moreover, our results showed that the drug Stamulumab (MYO-029), known as a potential MSTN inhibitor, was previously tested in clinical studies of subjects with myopathies." (PMID 31013615, 2019). "GC‐induced myopathy was observed in other animal studies and in patients, which involves proteolysis of muscle fibers due to activation of lysosomal and ubiquitin‐proteasome enzymes or by upregulation of myostatin, a negative regulator of muscle mass." (PMID 31044183, 2019). "Therefore, targeting myostatin with specific monoclonal antibodies may have a therapeutic rationale, as demonstrated by several trials in patients with primitive or secondary myopathies and age-related sarcopenia." (PMID 38201893, 2023). "Indeed, dietary lutein has been associated with a reduction in oxidative stress and inflammation in rats, increased muscle fiber diameter in chickens, and may act through downregulation of MSTN, which is a negative regulator of muscle growth that is dysregulated in several myopathies." (PMID 41373724, 2025). "Numerous studies breeding myostatin-null mice to several mouse models of inherited and acquired myopathies have shown various beneficial and non-beneficial effects." (PMID 21798096, 2011). "In addition, lower myostatin signalling activity has recently been reported in patients with inflammatory myopathies as compared with healthy subjects, and there was no clear association between the activity of the myostatin signalling pathway and the functional state of the patients." (PMID 36166425, 2022). "Similar to TGF-β1 and MSTN, perturbations of MAPK signaling have been documented in several myopathies, but not many studies exist examining the effects of inhibition on disease progression." (PMID 21798096, 2011).
heart disease (8 papers, 2018 to 2025). "The role of myostatin has also been explored in humans across different types of heart diseases with cardiac remodeling and reduced LV ejection fractions, and a strong association has been found between the severity of the disease and myostatin overexpression." (PMID 37958492, 2023). "Myostatin is increased in a number of chronic disease including COPD and cardiac diseases where muscle loss occurs." (PMID 28984049, 2018).
cardiovascular diseases (6 papers, 2016 to 2024). "In terms of cardiovascular disease, the upregulation of myostatin in the cardiomyocytes surrounding an ischemic infarction in sheep was shown in 1999 and myostatin protein and mRNA in skeletal muscle and myocardium were increased in a rat-model of volume overload heart failure." (PMID 33802348, 2021). "Another report suggested that higher GDF11/myostatin circulating levels were associated with a lower risk of cardiovascular events and death, and a separate study demonstrated that GDF11 did not decline with age and was associated with a higher risk of cardiovascular diseases." (PMID 29783655, 2018).
infection (6 papers, 2017 to 2025). The state of being infected such as from the introduction of a foreign agent such as serum, vaccine, antigenic substance or organism. "After 3 months, we observed that AAV2/8‐dnMstn infection markedly induced exogenous dominant negative MSTN expression in the livers of AAV2/8‐dnMstn‐injected mice." (PMID 40717541, 2025). "A stacked histogram showing the percentage distribution of MSTN expression in muscle after infection with 1 × 1010 vg of the rAAV9-sgMstn1 indicated 85%, 73.2%, 59.8% at 6, 8, 10 weeks." (PMID 34590222, 2021). "And the percentage distribution of MSTN expression in muscle after infection with 1 × 1011 vg of the rAAV9-sgMstn1 indicated 80.43%, 67.5%, 51.33% at 6, 8, 10 weeks." (PMID 34590222, 2021). "The infection of a single-stranded RNA virus, NNV, significantly upregulated the myostatin promoter activities of the full-length (P-1835) and different deletion promoter constructs (P-1235, P-894 and P-791)." (PMID 29036192, 2017). "In this study, we identified several proteins (FABP4, LEP, RARRES2, MSTN, C2, SELE and IL6) that belong to a family of chronic pro-inflammatory cytokines and are primarily produced in response to infection or stress, some of which are mainly produced by adipose tissue (FABP4, LEP and RARRES2)." (PMID 38548792, 2024). "Consequently, myostatin was not good predictor of infection; however, its decline was a strong independent predictor of C/A (versus C/S) CD (AUC = 0.998; R2C&S = 0.716)." (PMID 34479416, 2021).
kidney disease (4 papers, 2008 to 2022). "The chronicity and severity of kidney disease, resultant serum IS level, and baseline muscle mass, which is reflected by the myostatin level, can influence the efficacy of AST‐120 in improving muscle strength." (PMID 34862753, 2022). "In a pre-clinical model of kidney disease (5/6 nephrectomy), there was increased myostatin expression and muscle atrophy which was improved with an anti-myostatin peptide." (PMID 27486747, 2016). "In summary, we demonstrated in a slow progressing, naturally occurring model of CKD in animals with severe kidney disease there is enhanced activation of skeletal muscle stem cells, increased myostatin expression and downstream activation of the atrogenes, Atrogin-1 and MuRF1." (PMID 27486747, 2016). "However, there is limited information about the influence of kidney disease on myostatin expression and function beyond changes in myostatin mRNA." (PMID 17987322, 2008). "The absence of association between MSTN expression and proteinuria, and the lack of altered regulation of MSTN in renal tissues of nondiabetic kidney disease suggests that the observed MSTN activation in DN was not consequence of protein excretion." (PMID 32286342, 2020).
musculoskeletal disease (3 papers, 2021). "BMD was significantly increased in myostatin-deficient mice, and the use of myostatin inhibitors restricted bone loss as well as muscle loss in a number of musculoskeletal disease models." (PMID 33807573, 2021).
bacterial infection (2 papers, 2020 to 2024). "Experimental studies indicate a relationship between increased myostatin levels and more severe viral and bacterial infections." (PMID 38672190, 2024).
degenerative diseases (2 papers, 2007 to 2013). "In line with this notion, several groups have attempted to elucidate the intervention of myostatin in muscle regeneration after injury or in degenerative diseases." (PMID 19412331, 2007). "Although the mechanism by which myostatin regulates muscle regeneration has yet to be clarified, these findings highlight the importance of myostatin in the process of muscle repair both after injury or in degenerative diseases." (PMID 19412331, 2007). "By analogy with myostatin and muscle regeneration, anti-GDF11 therapy might be of value in neurodegenerative disease; however we still require an in-depth knowledge of how this growth factor regulates neural stem cell function." (PMID 24244313, 2013).
muscular disorders (2 papers, 2015 to 2022). "Furthermore, our findings confirm that MSTN inhibition can provide therapeutic benefits for those with debilitating muscular disorders." (PMID 35457038, 2022). "The master regulatory functions of myostatin identified in this study should now be explored at the biochemical level to identify details of the regulatory networks, especially because of their potential to assist in the development of muscular disorders." (PMID 25710176, 2015).
genetic muscle disease (1 paper, 2024). "For instance, studies have linked reduced serum myostatin levels to the progression of genetic muscle disease, possibly attributed to the downregulation of the myostatin pathway as a compensatory mechanism in response to muscle wasting or atrophy." (PMID 39407757, 2024).
muscling (1 paper, 2017). "In the same year, the bovine MSTN gene was mapped to the mh locus by genetic linkage, which strongly suggested that MSTN may be the gene that causes double muscling in cattle." (PMID 28344633, 2017).